SAMD7 (sterile alpha motif domain containing 7)
Description:
Component of a Polycomb group (PcG) multiprotein PRC1-like complex, essential for establishing rod photoreceptor cell identity and function by silencing nonrod gene expression in developing rod photoreceptor cells. Via its association with the PRC1-like complex, promotes epigenetic repressive marks H3K27me3 and H2AK119ub marks in nonrod genes, silencing their transcription. Represses Crx-controlled photoreceptor-specific gene expression.
Synonyms: DKFZp686E1583; MDCD
Tractability: No criterion of Open Targets' tractability assessment is met for any kind of drug.
Gene: Protein-coding gene on chromosome 3 (169,911,572 to 169,939,175, forward strand). Ensembl gene ENSG00000187033.
Subcellular location: Nucleus; Cytoplasm
Gene Ontology:
Molecular function: protein binding; chromatin binding; DNA-binding transcription repressor activity, RNA polymerase II-specific; histone binding
Biological process: negative regulation of DNA-templated transcription; negative regulation of gene expression, epigenetic; retinal rod cell development; negative regulation of gene expression; negative regulation of transcription by RNA polymerase II
Cellular component: nucleus; cytoplasm; PRC1 complex
Genetic constraint (gnomAD): Loss-of-function variants: 20 observed, 24.57 expected, observed/expected ratio (o/e) 0.81, 90% interval 0.57 to 1.18. The upper end of that interval is the gene's LOEUF score, 1.18, which puts it in group 5 of 6, group 1 being the genes least tolerant of losing a copy. Missense variants: 368 observed, 372.94 expected, observed/expected ratio (o/e) 0.99, 90% interval 0.9 to 1.08. Synonymous variants: 140 observed, 135.28 expected, observed/expected ratio (o/e) 1.03, 90% interval 0.9 to 1.19.
Homologues: Orthologues: chimpanzee SAMD7 (98% identical), macaque SAMD7 (95% identical), dog SAMD7 (79% identical), rabbit SAMD7 (75% identical), pig SAMD7 (72% identical), guinea pig SAMD7 (69% identical), mouse Samd7 (66% identical), rat Samd7 (63% identical), tropical clawed frog samd7 (36% identical), zebrafish samd7 (36% identical), Drosophila melanogaster l(3)mbt (14% identical), Caenorhabditis elegans lin-61 (8% identical), and 2 more. Paralogues in human: SAMD11 (24% identical), PHC3 (17% identical), PHC2 (16% identical), PHC1 (15% identical), SFMBT2 (14% identical), L3MBTL4 (14% identical), L3MBTL3 (13% identical), SFMBT1 (13% identical), SCMH1 (12% identical), L3MBTL1 (12% identical), SCML2 (10% identical), SCML4 (10% identical), and 6 more.
Diseases named in the same sentence as SAMD7 in open-access papers:
SAMD7 is named in the same sentence as 7 diseases in open-access papers, as found by Europe PMC text mining. Sharing a sentence is not in itself a finding about the gene and the disease. The quoted sentences say what the papers report.
liver cancer (1 paper, 2019). An epithelial or non-epithelial malignant neoplasm that arises from the liver. "To better understand the biological function of SMAD7 in inhibiting liver cancer development and progression, we generated a protein–protein interaction network for SAMD7 by using the cBioPortal database." (PMID 31711043, 2019).
retinal dystrophies (1 paper, 2016). "Identification of SAMD11 as causative gene in two RP families highlights a putatively important role for other SAM-related proteins, such SAMD7, in the pathogenesis of the retinal dystrophies." (PMID 27734943, 2016).
tumor (2 papers, 2021 to 2023). "Besides, we investigated the expression of SMAD7 in CRC using GEPIA, which indicated that SAMD7 expression was lower in tumor tissues compared to normal tissues in COAD, as well as READ." (PMID 36550779, 2023). "SMAD2 knockdown effectively increases this effect of SMAD3/4, and inducing the transcription of SMAD7 may prevent TGF-β-induced EMT of tumor cells; thus, SAMD7 and SAMD2 may play a role in EMT to regulate tumor metastasis." (PMID 34367975, 2021).
SAMD7 also shares sentences with these, for which no sentence is quoted: Bardet-Biedl syndrome (1 paper); cardiac hypertrophy (1); lung carcinoma (1); retinal degeneration (1).